AMZ2 (archaelysin family metallopeptidase 2)
Description:
Probable zinc metalloprotease.
Tractability: PROTAC: ubiquitination databases record sites on it; its protein half-life has been measured.
Gene: Protein-coding gene on chromosome 17 (68,205,481 to 68,257,712, forward strand). Ensembl gene ENSG00000196704.
Subcellular location (Human Protein Atlas): Nucleoplasm; Cytosol; Nuclear bodies
Gene Ontology:
Molecular function: metallopeptidase activity; peptidase activity
Biological process: proteolysis
Cellular component: nucleoplasm
Genetic constraint (gnomAD): Loss-of-function variants: 24 observed, 33.63 expected, observed/expected ratio (o/e) 0.71, 90% interval 0.52 to 1. The upper end of that interval is the gene's LOEUF score, 1, which puts it in group 4 of 6, group 1 being the genes least tolerant of losing a copy. Missense variants: 363 observed, 414.42 expected, observed/expected ratio (o/e) 0.88, 90% interval 0.8 to 0.95. Synonymous variants: 126 observed, 142 expected, observed/expected ratio (o/e) 0.89, 90% interval 0.77 to 1.03.
Homologues: Orthologues: chimpanzee AMZ2 (98% identical), macaque AMZ2 (96% identical), guinea pig AMZ2 (88% identical), rabbit AMZ2 (88% identical), dog AMZ2 (86% identical), pig AMZ2 (84% identical), rat Amz2 (79% identical), mouse Amz2 (79% identical), zebrafish AMZ2 (46% identical). Paralogues in human: AMZ1 (35% identical).
Diseases named in the same sentence as AMZ2 in open-access papers:
AMZ2 is named in the same sentence as 1 disease in open-access papers, as found by Europe PMC text mining. Sharing a sentence is not in itself a finding about the gene and the disease.
cancer (2 papers, 2023 to 2024). A tumor composed of atypical neoplastic, often pleomorphic cells that invade other tissues.